FZD4 (frizzled class receptor 4)
Diseases named in the same sentence as FZD4 in open-access papers (continued):
Sharing a sentence is not in itself a finding about the gene and the disease.
tumor (continued). "Furthermore, we identified the Norrin/Fzd4 pathway as an endogenous signalling axis that can be manipulated to target this pre-tumor/stromal relationship." (PMID 27823583, 2016). "Thus, given its known function in signalling to endothelial cells and its expression pattern in GNPs and MB, the Norrin/Fzd4 axis is well-positioned to mediate neural-endothelial cell crosstalk within the Shh-MB lesion and tumor microenvironment." (PMID 27823583, 2016). "Therefore, we tested Fzd4’s level and found that Lin28b could only be detected in both Wnt5a and Fzd4 high-‍expressed tumor cells lines, indicating that intact Wnt5a-Fzd4 pathway is essential for activation of Lin28b in PDAC." (PMID 37898598, 2023). "However, FZD4 also plays a role in tumor progression, migration, and invasion." (PMID 34604862, 2021). "Thus, acute disruption of Fzd4 promotes the conversion to an angiogenic, pro-tumor stroma within seven days, suggesting that continued maintenance of Norrin/Fzd4 signalling creates a tumor-protective microenvironment." (PMID 27823583, 2016). "The IHC figures showed that the tumor tissue of sh-NLGN1-AS1 group exhibited decreased ki-67 and FZD4 staining than those of NC group." (PMID 36170021, 2022). "We further used DAVID to search for those genes from the predicted target genes that are related to tumor, and found the target genes of LYN, RASAL2, FZD4, and GNG2 for further study." (PMID 35174106, 2022). "In this system, FZD4-induced WNT signaling is primarily at the invasive, exterior portion at the tumor suggesting FZD4 plays a role in tumor initiation and metastasis." (PMID 34604862, 2021). "A large number of oncogenes as target genes of miR-505 in tumor cells, including TGF-α, HMGB1, FZD4, IGF1R, WNT7B, MAP3K3, NRCAM, and RUNX2, have been recognized as direct target genes of miR-505." (PMID 33520999, 2020). "We found that FZD4-SNP-3′UTR over-expression in H1299 and Calu-6 cells significantly inhibited these tumor cell-induced colony formation compared with FZD4-WT-3′UTR over-expression." (PMID 28831115, 2017). "We found that in tumor tissues with circ_0017109 knockdown, FZD4, β-catenin and non-phospho β-catenin, cyclin D1, and c-Myc showed significant reduction, and a higher level of cleaved caspase-3 and a lower level of Bcl-2 were also detected." (PMID 36434577, 2022). "At the primary tumor site, cancer cells often take on mesenchymal properties, termed epithelial mesenchymal transition (EMT), which are regulated in part by the Wnt receptor FZD4." (PMID 34685470, 2021). "In summary, circPRKAR1B may crucially affect tumour proliferation and lung metastasis in OS through EIF4A3-induced circPRKAR1B/miR-361-3p/FZD4 axis." (PMID 34716310, 2021). "High tumor expression of LMAN2, FZD4, FZD5, or STT3A was associated with no significant PFS increase after IP compared to IV chemotherapy." (PMID 26883286, 2016). "In addition, proteins of the Frizzled family, such as FZD4 and FZD5, participate in the WNT signaling pathway and inflammatory processes in nervous tissue and are related to tumor initiation and cell proliferation of glioma cells, respectively, and can modulate tumor progression." (PMID 35784465, 2022). "Our data suggest that FZD4-miR-SNP loci may significantly influence overall survival in NSCLC patients by specifically interacting with miR-204 and modulating FZD4 expression and cellular function in the Wnt-signaling-driven tumor progression." (PMID 28831115, 2017). "The association analyses between NHERF1 and the other markers revealed a positive direct relation between cNHERF1 and FZD4, LRP5, LRP6, and TCF1 expression, but not with β-catenin, suggesting a possible novel tumor progression mechanism, that involves Wnt signaling components." (PMID 31336689, 2019).
cancer (41 papers, 2007 to 2025). A tumor composed of atypical neoplastic, often pleomorphic cells that invade other tissues. "Further investigation of the mechanisms underlying this antitumor activity revealed that Sja-miR-71a exerts its function by targeting FZD4 gene that is a receptor of Wnt pathway and associated with cancer cell viability and migration." (PMID 35174106, 2022). "The dysregulation of FZD4 was mentioned to be associated with the development of human diseases, including cancer." (PMID 34507595, 2021). "Generally, the miRNA targets of FZD4 were related to cancer, drug resistance, embryonic development, and aging." (PMID 40667070, 2025). "Let-7a target gene (WNT7A, β-catenin, IRS2, and FZD4) expression significantly increased in T2–T4 compared with pT1 as let-7a miRNA inhibition stimulates FZD4 and Wnt/β-catenin pathway in cancer cells." (PMID 36140796, 2022). "As FZD4 is a key receptor of Wnt signaling pathway and its potential function in carcinoma, we then focused on this gene for further investigation." (PMID 35174106, 2022). "With numerous miRNAs already associated with Fzd4, there is strong potential for further investigation into circRNA that influences Fzd4 signaling in cancer." (PMID 34671643, 2021). "The presence of FZD4 in premalignant tissues along with the ability of FZD4 to induce cancer cell EMT highlights FZD4’s potential in future chemopreventive studies." (PMID 34604862, 2021). "Little is known about the cancer tissue expression of FZD4, LRP5, LRP6 proteins, and we assessed their behavior for the first time in a clinical BC cohort." (PMID 31336689, 2019). "In addition to the already-known targets, we further identified relevant cancer-associated genes; such as, FGFR1, VEGFA, WNT9A, and FZD4." (PMID 35132075, 2022). "Data suggest that FZD4/9 enhances HCC cell proliferation and cell motility in vitro while FZD4 might also confer cancer stemness properties in HCC." (PMID 29361730, 2018). "SNP rs713065(C) in the miR-204 binding site in the FZD4 3′UTR might shed light on targeting at Wnt-CTNNB1 signaling anti-cancer treatment." (PMID 28831115, 2017). "Previous studies show that ERG regulates the expression of frizzled class receptor 4, E-cadherin, vimentin, ras homolog family member A, vascular endothelial growth factor receptor 2, and zinc finger E-box binding homeobox 1/2 during cancer metastasis and epithelial–mesenchymal transition process." (PMID 29773901, 2018). "Members in FZD family including FZD2, FZD4, FZD7, FZD8 and FZD10 have been demonstrated to mediate cancer cell epithelial-mesenchymal transition (EMT)." (PMID 33618713, 2021). "Additionally, the top hub genes identified in the PPI network of FZD4 miRNA targets, including MYC, EGFR, MDM2, and CDK1, were also involved in many aspects of cancer progression." (PMID 40667070, 2025). "Furthermore, low levels of let-7a-5p miRNA and high levels of FZD4, WNT7A, and b-Catenin genes were correlated with worse cancer-specific survival." (PMID 38396855, 2024). "Furthermore, underexpression of Let7b induces cancer stemness in HCC, cell proliferation, migration, and invasion through activation of Wnt signaling via the upregulation of FZD4 in an HCC cell line model." (PMID 29361730, 2018). "Moreover, the downregulation of vascular endothelial growth factor (VEGF), a mediator of angiogenesis, and Frizzled Class Receptor 4 (FZD4), may also contribute to further reducing invasiveness and cancer progression." (PMID 37310937, 2023). "PIK3CA-mutant cancers displayed higher expression of 12 of the 17 Wnt genes compared to PIK3CA wild-type tumors, including five Wnt target genes (LEF1, MYCN, FZD7, SFRP2, and TNFRSF11B) and seven Wnt signaling components (TCF7L1, TCF7L2, CTNNB1, FZD4, SFRP1, WNT5A, and MSX2)." (PMID 34035258, 2021).
retinopathies (5 papers, 2015 to 2025). "Mutations in Fzd4, Lrp5, Tspan12, or Ndp in mice result in retinopathies with remarkable similarity to human diseases, including aberrant development of the retinal vasculature, BRB defects, and impaired vision." (PMID 36432666, 2022). "FEVR is an inherited retinal disorder characterized by incomplete retinal vascular development and secondary retinal changes, and has been reported to be associated with Wnt signaling genes (FZD4, TSPAN12, and NDP) polymorphism." (PMID 35022017, 2022).
infection (3 papers, 2022 to 2023). The state of being infected such as from the introduction of a foreign agent such as serum, vaccine, antigenic substance or organism. "Comparing the time-dependent changes between 3 hours and different times after infection, several genes like FZD4, LPR4, and MUC13 which were upregulated compared to the uninfected controls were also upregulated over time." (PMID 37615437, 2023).
female reproductive diseases (1 paper, 2020). "These coding proteins, especially FZD4, represent promising therapeutic targets for treatment of female reproductive diseases and improvement of female fertility." (PMID 32415058, 2020).
neurological diseases (1 paper, 2023). "Overall, these studies develop a highly optimized FZD4-selective WNT surrogate and suggest that FZD4 stimulation could be of potential use in treating pathologic BBB compromise in neurological diseases." (PMID 37268690, 2023).
vascular disorder (1 paper, 2016). A general term used to describe any disease affecting blood vessels]. "Mutations in Norrin/Fzd4 pathway components cause a spectrum of human pathologies, including vascular disorders with retinal and cerebellar phenotypes." (PMID 27823583, 2016).
FZD4 also shares sentences with these, for which no sentence is quoted: acute myocardial infarction (2 papers); age-related macular degeneration (2); basal cell carcinoma (2); retinal vascular disorder (2); Alzheimer disease (1); Arthritis (1); Barth syndrome (1); capillary malformation (1); cerebellar degeneration (1); clear cell renal cell carcinoma (1); colorectal polyps (1); congenital myasthenic syndrome (1); embryonal carcinoma (1); endometrial cancer (1); foveal hypoplasia (1); glioblastoma (1); hearing loss (1); hepatoblastoma (1); Hirschsprung disease (1); Hyperinsulinemia (1); inherited diseases (1); keloid (1); metastatic cancer (1); MLCRD) syndrome (1); multiple sclerosis (1); pulmonary arterial hypertension (1); renal carcinoma (1); retinal detachment (1); Retinal hemorrhage (1); retinoschisis (1).
A further 7 diseases each share a sentence with FZD4 in 1 paper.